CASC6 (cancer susceptibility 6)
Gene: Long non-coding RNA gene on chromosome 6 (91,557,292 to 91,690,428, reverse strand). Ensembl gene ENSG00000224944.
Diseases named in the same sentence as CASC6 in open-access papers:
CASC6 is named in the same sentence as 1 disease in open-access papers, as found by Europe PMC text mining. Sharing a sentence is not in itself a finding about the gene and the disease. The quoted sentences say what the papers report.
cancer (1 paper, 2024). A tumor composed of atypical neoplastic, often pleomorphic cells that invade other tissues. "One downstream gene, CASC6, codes for cancer susceptibility 6, which, although the name may indicate otherwise, has an unknown function." (PMID 39008506, 2024).